MTOR (mechanistic target of rapamycin kinase)
Diseases named in the same sentence as MTOR in open-access papers (continued):
Sharing a sentence is not in itself a finding about the gene and the disease.
breast cancer (continued). "miR-147 downregulation in breast cancer promotes Akt/mTOR signaling, while miR-200c enhances breast tumor cell sensitivity to doxorubicin and inhibits EMT and metastasis." (PMID 39858015, 2025). "In ERα-positive breast cancer, inhibition of the ERα-mTOR pathway is an effective therapeutic strategy." (PMID 40937413, 2025). "This axis also influences the sensitivity of breast cancer cells to mTOR inhibitors, thereby presenting itself as a promising molecular target for breast cancer treatment and a therapeutic target for mTOR inhibitor-resistant patients." (PMID 38664392, 2024). "To summarize, mTOR inhibitors like everolimus have shown promise in treating advanced breast cancer." (PMID 38256428, 2024). "A range of flavonoids have been identified as inducers of autophagy in breast cancer cells by inhibiting the Akt/mammalian target of the rapamycin (mTOR) pathway." (PMID 38475417, 2024). "Terpenes also exhibited modulatory action on the PI3K/Akt/mTOR pathway by inhibiting its activity, leading to apoptosis and inhibition of cellular proliferation in malignant melanoma and breast cancer cells." (PMID 39519654, 2024). "MRPL13 promotes cell proliferation, migration, and epithelial–mesenchymal transition (EMT) in breast cancer by activating the PI3K/AKT/mTOR signaling pathway." (PMID 39770478, 2024). "YBX1 collaborates with oncogenic lncRNA SBF2-AS1, driving breast cancer cell proliferation via PI3K/AKT/mTOR." (PMID 38255791, 2024). "This capability facilitates the design of assays that can analyze additional proteins and critical signaling pathways, such as those involved in the Her2/PI3K/Akt/mTOR signaling pathway in breast cancer." (PMID 39304879, 2024). "PIK3CA, one of the most commonly mutated genes in breast cancer, especially in HR+ and HER2+ subtypes, drives hyperactivation of the PI3K/AKT/mTOR pathway, making it a key target for PI3K inhibitors." (PMID 39850811, 2024). "The PI3K/AKT/mTOR pathway also plays a role in cell motility, migration, and invasion, contributing to the metastatic potential of breast cancer cells." (PMID 39408832, 2024). "A membranaceus extract has also been reported to inhibit breast cancer cell proliferation via the PI3K/AKT/mTOR signaling pathway." (PMID 38466979, 2024). "Dual PI3K/mTOR inhibition has shown superior efficacy compared to targeting PI3K alone in combination with ICB in preclinical mouse models of breast cancer." (PMID 38711203, 2024). "Triosephosphate isomerase was found to be involved in PI3K/AKT/mTOR signalling pathway and hence breast cancer development, which supports the significance of the finding for triosephosphate isomerase in this study." (PMID 38249992, 2024). "Amentoflavone inhibits TNFα-induced Gli1 activation in breast tumor cells, resulting in reduced invasiveness of human breast cancer cells by interceding AKT/mTOR/S6K1 signaling and blocking the migration and invasiveness of MDA-MB-231 cells." (PMID 39257397, 2024). "The PI3K/Akt/mTOR pathway is also implicated in the development of resistance to endocrine therapy, further supporting the rationale for mTOR inhibition in the treatment of ER + breast cancer." (PMID 38904918, 2024). "Inhibiting HMMR expression through compounds targeting key signaling pathways, such as mTOR, presents innovative therapeutic avenues, particularly in breast cancer." (PMID 38576486, 2024). "PI3K/AKT/mTOR pathway plays a significant role in sustaining endocrine resistance and is the target of many new drugs for patients with ER+ breast cancer." (PMID 38459605, 2024). "The Clarke laboratory first showed that TSC2/AMPK mediated mTOR inhibition occurred in antiestrogen treated sensitive and resistant breast cancer cells." (PMID 38567308, 2024). "Further research is crucial to elucidate the diverse mechanisms through which cytokines, IGF-1, mTOR, and AKT levels contribute to the increased breast cancer risk." (PMID 38254789, 2024).
breast cancer (continued). "Ye and co-workers have reported that RAC induces autophagy in breast cancer cells by inhibiting the PI3K/AKT/mTOR pathway." (PMID 38764054, 2024). "Rapamycin, an mTOR inhibitor, regulates primordial follicle activation and exhibits potential inhibitory effects against breast cancer cell proliferation." (PMID 38734930, 2024). "Studies have shown that mTOR is frequently overexpressed in breast cancer tissues compared to normal breast tissues." (PMID 39850811, 2024). "Above findings indicate that autophagy, EMT and PI3K/Akt/mTOR signalling are involved in the pathogenesis of breast cancer." (PMID 39084065, 2024). "The PI3K/Akt/mTOR pathway plays a crucial role in breast cancer biology and pathogenesis, with its dysregulation contributing to tumor initiation, progression, and resistance to therapy." (PMID 39408832, 2024). "The activation of IGF2/IGF-1R/IRS1 signaling is one of the key mechanisms underlying anti-HER2 resistance in breast cancer, with this activation occurring through the AKT/mTOR pathway, which in turn activates Src kinase." (PMID 39769140, 2024). "This indicates that harmine induces apoptosis in breast cancer cells by inhibiting the PI3K/AKT/mTOR signaling pathway." (PMID 38590646, 2024). "The FS diet altered microbiota-miRNA relationships which targeted pathways related to the PI3K-Akt-mTOR pathway and genes previously found to be related to breast cancer." (PMID 38059614, 2024). "Inhibition of the PI3K/AKT/mTOR axis has been shown to elicit senescence in breast cancer, resulting in the secretion of SASP factors (CCL2, CXCL1, CXCL8, IL‐6), which induce an M2‐like polarisation." (PMID 39270064, 2024). "The PI3K/AKT/mTOR signaling is a vital pathway in cancer cells that regulates cell growth, migration, and invasion in breast cancer." (PMID 38302629, 2024). "Genes involved in the enrichment of the PI3K-Akt-mTOR pathway included Runx2 and Skp2, which are involved in mammary gland development and breast cancer." (PMID 38059614, 2024). "We discovered that incubation with 3b downregulates the number of cells with active mTOR in a dose dependent manner in both breast cancer cell lines at 24 h." (PMID 38700244, 2024). "The PI3K/AKT/mTOR pathway undergoes significant upregulation in various cancers, including gallbladder cancer and breast cancer, playing a pivotal role in promoting tumor progression." (PMID 39210450, 2024). "Among the identified proteins, RNH1, which has been reported to regulate the expression of mTOR in breast cancer, was of interest." (PMID 39513392, 2024). "Our results demonstrate that HDAC inhibitor and PI3K inhibitor can overcome breast cancer resistance to tamoxifen through down-regulation of the PI3k/Akt/mTOR signaling pathway." (PMID 38645502, 2024). "The PI3K/Akt/mTOR signaling cascade is hyperactivated in many solid tumors, including breast cancer, contributing to cancer progression and resistance to pro-apoptotic therapies." (PMID 38218922, 2024). "These networks reveal the importance of the therapeutic modulation of PI3K/AKT/MTOR, ETV7, and YAP/TAZ, as they alter several oncogenes and cellular pathways and that can cause several diseases (including breast cancer); details given below." (PMID 38791386, 2024). "In two phase III randomized placebo-controlled BELLE-2 and BELLE-3 trials, the combination of buparlisib with fulvestrant was evaluated in HR-positive, HER2-negative postmenopausal breast cancer patients who progressed on AI or mTOR inhibitors." (PMID 38396649, 2024). "This nanosystem provides insights into integrating mTOR inhibitors and photosensitizers for safe and effective breast cancer treatment in clinical settings." (PMID 39235716, 2024). "The PI3K/AKT/mTOR signaling pathway is another one with an impact on breast cancer development; more PI3K mutations are features of breast cancer predisposition." (PMID 39598664, 2024).
breast cancer (continued). "On a molecular level, one of the most dysregulated signaling pathways in breast cancer is the PI3K/Akt/mTOR pathway." (PMID 38672636, 2024). "The PI3K/AKT/mTOR pathway was estimated to be upregulated in up to 70% of all breast cancers, including TNBC but inhibitors of this pathway have been approved so far only for ER+ breast cancer and have not shown clinical efficacy in TNBC." (PMID 39541354, 2024). "The PI3K/AKT/mTOR signaling pathway stimulates proliferation and tumor growth in both ovarian and breast cancer cells." (PMID 39770406, 2024). "Quercetin can also inhibit breast cancer progression through Akt-mTOR pathway-mediated autophagy-induced inhibition of cell migration and glycolysis." (PMID 38177197, 2024). "The investigation revealed the ability of these derivatives to potentiate therapeutic anticancer effects by targeting the PI3K/Akt/mTOR signaling pathway, which is crucial for cell signaling, proliferation, survival, and metabolism in breast cancer." (PMID 38773663, 2024). "For example, targeting mammalian target of rapamycin (mTOR) can control the growth of various tumors including breast cancer, kidney cancer, neuroendocrine cancer and so on." (PMID 38218942, 2024). "In our results, CBG reduced mTOR protein expression and, in line with this, some studies demonstrated that CBD inhibits the mTOR signaling pathway in breast cancer and human glioma." (PMID 38396679, 2024). "It has been proven that Paclitaxel can modulate the proliferation and migration of breast cancer cells via the mTOR signaling pathway." (PMID 38418940, 2024). "The PI3K, AKT, and mTOR (PAM) pathway is frequently dysregulated in breast cancer (BC) to accommodate high catabolic and anabolic activities driving tumor growth." (PMID 38839777, 2024). "These trials have addressed breast cancer, colon cancer, lung cancer, ovarian cancer, pancreatic cancer, prostate cancer, and urothelial cancer, utilizing various mTOR inhibitors such as rapamycin, everolimus, metformin, and sirolimus." (PMID 39349424, 2024). "This process was mediated by the down-regulation of long noncoding RNA Colon-cancer-associated transcript-1 (CCAT1) and inactivation of the PI3K/Akt/mTOR pathway in treated breast cancer cells." (PMID 39539439, 2024). "Previous studies have observed that mTORC1 is overactive in various types of cancers, such as breast cancer and colon cancer, and confirmed that mTOR pathway plays an obvious role in promoting the development and occurrence of cancer." (PMID 38267663, 2024). "The ST8SIA1 (GD3 synthetase) gene was shown to regulate GD2 biosynthesis; and when it is knocked out, the inhibition of the FAK/AKT/mTOR signaling pathway and suppression of growth and metastasis in breast cancer is observed." (PMID 38558810, 2024). "Cannabidiol has been found to induce NOX4-mediated release of mitochondrial ROS and promote caspase-dependent apoptosis through the activation of ER stress signaling pathway and the inhibition of the mTOR signaling pathway in breast cancer cells." (PMID 39796030, 2024). "This study demonstrates that SF3B3-regualted mTOR splicing contributes to autophagy in SF3B3-knockdown breast cancer cells." (PMID 38671459, 2024). "Triptolide induces autophagy and affects the phosphorylation of p38 mitogen-activated protein kinase, extracellular signal-regulated kinase (Erk) 1/2, and mammalian target of rapamycin (mTOR), leading to autophagy and apoptosis in breast cancer cells." (PMID 38993643, 2024). "Everolimus (EVE), an mTOR inhibitor, has demonstrated efficacy in enhancing the effects of endocrine therapy in both pre-clinical models and clinical trials in breast cancer." (PMID 38904918, 2024). "HDAC inhibitors inhibited the survival of breast cancer drug-resistant cells, invasion, migration, and angiogenesis by inhibiting the PI3k/Akt/mTOR signaling pathway." (PMID 38645502, 2024).
breast cancer (continued). "mTOR-xenograft mouse models of breast cancer and glioblastoma suggest that Rapalink-1 is more sensitive than rapamycin and AZD8055, but large sample clinical data for this drug have not been reported." (PMID 38421832, 2024). "We examined the relationship between pDNA/tachyplesin and the mTOR signaling pathway in both breast cancer cells and normal cells." (PMID 38691208, 2024). "As a result, CTSD research in breast cancer has been active, confirming that this protein is connected to the mTOR pathway." (PMID 38361124, 2024). "Remarkably, the administration of oleocanthal resulted in a notable reduction in phosphorylated mTOR within the metastatic breast cancer cell line (MDA-MB-231)." (PMID 39203892, 2024). "Tamoxifen induces ACD in breast cancer cells in association with Akt downregulation; conversely, autophagy is involved in tamoxifen resistance via the activation of the PI3K/Akt/mammalian target of rapamycin (mTOR) signaling pathway." (PMID 38473345, 2024). "IC2 stimulated autophagy in these breast cancer cell lines via the AMPK/mTOR pathway by phosphorylation of AMPK and inhibition of mTOR." (PMID 39539439, 2024). "Subsequently, the ubiquitinated TBK1 decreases its interaction with mTOR and attenuates mTOR signaling pathway, thus inhibiting the proliferation of breast cancer cells." (PMID 39061024, 2024). "We previously reported that KCa1.1 transcription was activated by the inhibition of the Akt/mTOR signaling pathway in breast cancer MDA-MB-453 cells." (PMID 38892210, 2024). "The PI3K-Akt-mTOR pathway has also been shown to play a role in breast cancer therapy resistance, with inhibition of mTOR resulting in restored sensitivity to tamoxifen." (PMID 38059614, 2024). "The PI3K/AKT/mTOR pathway regulates cell growth and survival, frequently dysregulated in breast cancer, making it an attractive therapeutic target." (PMID 38474678, 2024). "In conclusion, this study demonstrated that mTOR inhibitors exert an ovario-protective effect during cyclical cyclophosphamide regimens, which have high antitumour effects as single agents in breast cancer." (PMID 38734930, 2024). "Desialylated EPCAM promotes apoptosis in breast cancer cells by activating the PI3K/AKT/mTOR signaling pathway." (PMID 39605916, 2024). "This study offers valuable insights into the distinct mRNA expression profiles and miRNA regulators of the PI3K/AKT/mTOR signaling pathway across various breast cancer subtypes." (PMID 39850811, 2024). "The PI3K/AKT/mTOR signalling pathway is one of the most frequently activated pathways in breast cancer and also plays a central role in the regulation of several physiologic functions." (PMID 38927964, 2024). "The Akt/mTOR (mechanistic target of rapamycin) pathway is often altered in breast cancers and is an important target for cancer therapy." (PMID 39594738, 2024). "In TNBC, Quercetin suppresses breast cancer cell growth and survival by targeting the Akt/mTOR/PTEN signaling pathway." (PMID 39257397, 2024). "AA is important in cancer development and activation of the PI3K/AKT/mTOR signalling pathway, whose over‐activation contributes to cell proliferation, growth, and cell migration in tumour cells, including breast cancer." (PMID 38443328, 2024). "The proposed strategy of targeting the mTOR pathway with rapamycin and Torin2, based on the strong correlation with HMMR and associated genes, introduces a novel and promising avenue for breast cancer treatment." (PMID 38576486, 2024). "Drugs like everolimus (an mTOR inhibitor) have been approved for use in certain breast cancers, highlighting the clinical relevance of targeting this pathway." (PMID 39408832, 2024). "Molecular targeted therapies have attracted attention, with anti-HER2 agents, CDK4/6 inhibitors, PARP inhibitors, and mTOR inhibitors being used to treat breast cancer." (PMID 39273689, 2024).
breast cancer (continued). "This pathway is frequently dysregulated in various cancers, such endometrial, cervical, lung, prostate, skin, and breast cancer, and mTOR is a key node and central regulator in this pathway." (PMID 38126764, 2024). "Our findings suggest that the PI3K/AKT/mTOR pathway and its miRNA regulators play crucial roles in breast cancer progression, particularly in aggressive subtypes like TNBC." (PMID 39850811, 2024). "Constitutive activation of the PI3K/AKT/mTOR signaling pathway has been found in multiple human cancers, including breast cancer, ovarian cancer, and colorectal cancer." (PMID 38302629, 2024). "It is proposed that cannabidiol induces endoplasmic reticulum stress and apoptosis by inhibiting the AKT/mammalian target of rapamycin (mTOR) signaling and enhances reactive oxygen species (ROS) generation for selected breast cancer cells." (PMID 39503169, 2024). "In breast cancer cells, elevated mTOR/c-MYC was previously shown to increase the expression of OGT and O-GlcNAcylation." (PMID 39388284, 2024). "This is particularly valuable for targeted pathway analysis, such as the PI3K/Akt/mTOR pathway in luminal breast cancer, where the precise measurement of pathway activation or inhibition can guide personalized therapy." (PMID 39304879, 2024). "Based on our previous results, on the induction of production of autophagosomes by 3b in both breast cancer cell lines, we have evaluated effect of this derivative on mTOR inhibition." (PMID 38700244, 2024). "In our analysis, we adopted a strategy to identify mRNAs related to the PI3K/AKT/mTOR pathway, which differentiate between the five subtypes of breast cancer, as well as transcripts common to all breast cancer types." (PMID 39850811, 2024). "Mutations in the PIK3CA gene, present in about 32% of Luminal B cases, can activate the PI3K/AKT/mTOR signaling pathway, contributing to breast cancer development and progression." (PMID 38256428, 2024). "IATL suppressed AKT/mTOR signaling pathway in colorectal cancer, regulated breast cancer cell proliferation via MAPK/NF-κB signaling pathway, and induced pancreatic cancer cell apoptosis by PI3K and Wnt signal pathway." (PMID 39382942, 2024). "The PI3K/Akt/mTOR pathway plays a central role in breast cancer cell proliferation and progression, providing a strong rationale for combining endocrine therapy with mTOR inhibition." (PMID 38904918, 2024). "The proposed link between HMMR and the mTOR pathway signifies the potential therapeutic significance of mTOR inhibitors in breast cancer treatment." (PMID 38576486, 2024). "In this study, we revealed that RPN1 promoted the proliferation and invasion of breast cancer cells by activating the PI3K/AKT/mTOR signaling pathway." (PMID 38302629, 2024). "In preclinical studies, elevated circulating levels of FGF2 have been linked to breast cancer development through the activation of oncogenic signalling pathways, including MAPK/ERK, cMYC and PI3K/AKT/mTOR." (PMID 39251829, 2024). "Our study suggested that HDAC inhibitor and PI3k inhibitor decrease the proliferation of tamoxifen-resistant breast cancer through inhibition of the PI3k/Akt/mTOR signaling pathway." (PMID 38645502, 2024). "Inhibitors targeting the PI3K/AKT/mTOR pathway are under clinical investigation and have shown promise in treating breast cancer." (PMID 39408832, 2024). "It is known that 18 ~ 20% of breast cancers are caused by the overexpression of HER2 oncogenes, which activate the PI3K/AKT/mTOR pathway, promoting tumor development." (PMID 39349424, 2024). "In this study, we identified that the STING-TBK1-mediated mTOR signaling pathway also played an important role in the proliferation of breast cancer cells." (PMID 39061024, 2024). "In breast cancer, PI3K/AKT/mTOR is frequently activated due to mutations in genes like PIK3CA and the amplification of receptor tyrosine kinases like HER2." (PMID 39770406, 2024).